CCHCR1 (coiled-coil alpha-helical rod protein 1)
Diseases named in the same sentence as CCHCR1 in open-access papers (continued):
Sharing a sentence is not in itself a finding about the gene and the disease.
chronic hepatitis B (1 paper, 2023). "Similar to CCHCR1, TCF19 has been associated with diseases, including diabetes, HBV-related chronic hepatitis B, cirrhosis, hepatocellular carcinoma, non-small cell lung cancer, squamous cell carcinoma of the head and neck (SCCHN) and colorectal cancer." (PMID 38128007, 2023).
hypotrichosis (1 paper, 2020). A congenital condition, usually due to genetic aberrations, that is characterized by a lack of hair growth on the head and/or body. "Although the deletion encompasses several other genes (C6orf15, PSORS1C1, PSORS1C2, CCHCR1 and part of TCF19), these patients show a phenotype resembling that of PSD without hypotrichosis." (PMID 31663161, 2020).
keratinization disorders (1 paper, 2024). "Besides immune aberrations, keratinization disorders could also be involved in the AA pathogenesis since an altered hair shaft constitutive molecule (i.e., coiled-coil alpha-helical rod protein 1 (CCHCR1) was identified." (PMID 38891839, 2024).
lung adenocarcinoma (1 paper, 2009). A carcinoma that arises from the lung and is characterized by the presence of malignant glandular epithelial cells. "In our previous studies, CCHCR1 expression was detected in nonproliferating cells in breast and lung adenocarcinomas: the hyperproliferation marker Ki67 was detected in adjacent, but not in the same cells as CCHCR1." (PMID 19551138, 2009). "We have previously shown that in breast and lung adenocarcinomas, CCHCR1 positive cells are Ki67 negative but this discrepancy may be due to differences between adenocarcinoma and SCC cells or the site organ of cancer." (PMID 19551138, 2009).
oral cancer (1 paper, 2023). "Specifically, for oral cancer, previous GWAS identified three loci in the HLA region, including rs3828805 (chromosome 6 position 32636120) and rs3135001 (6:32670136) in HLA-DQB1 (6p21.32) and rs1265081 (6:31111675) in CCHCR1 (6p21.33)." (PMID 36769103, 2023).
oral mucositis (1 paper, 2024). Inflammation of the mucous membranes of any of the structures in the mouth. "- SNP rs1265081 in CCHCR1 gene (allele A vs. C: OR = 1.41, 95% CIs = 1.08–1.86, p = 0.012) and rs3135001 (allele T vs. allele C: OR = 0.53, 95% CIs = 0.35–0.79, p = 0.002) were significantly associated with the occurrence of grade 3–4 oral mucositis." (PMID 38473311, 2024).
schizophrenia (1 paper, 2025). A major psychotic disorder characterized by abnormalities in the perception or expression of reality. "Similarly, CCHCR1 (cg09163778, associated with maternal schizophrenia PGS), located within the major histocompatibility complex (MHC) region, is of particular interest due to the MHC’s established role in immune regulation and its prior associations with schizophrenia." (PMID 40181191, 2025).
squamous intraepithelial lesions (1 paper, 2014). "More recently, an increase in CCHCR1 expression was observed in neoplastic cervical High-grade squamous intraepithelial lesions associated with HPV16." (PMID 24664238, 2014).
tumor (5 papers, 2009 to 2025). "We also demonstrated that the CCHCR1 gene in the non tumor and tumor cells of the cervical epithelium is highly polymorphic." (PMID 22218424, 2012). "CCHCR1 mRNA levels were determined in HaCaT cultures incubated with diverse bioactive agents with importance in tumor promotion, oxidative stress or psoriatic inflammation." (PMID 19551138, 2009). "The tumor promoters OA and menadione downregulated the expression of CCHCR1, Ki67, and EGFR mRNAs in HaCaT cells." (PMID 19551138, 2009). "KAs generally showed positive CCHCR1 staining especially in KCs of the pushing border in areas with a prominent lymphocyte infiltrate surrounding the tumor." (PMID 19551138, 2009). "Additionally, high mRNA expression levels of genes such as RAD54L (p = 3.3 × 10−6), MAST2 (p = 4.1 × 10−2), and CCHCR1 (p = 1.4 × 10−2) were associated with shorter DFS, further highlighting their role in tumor aggressiveness." (PMID 40227503, 2025). "However, in grade III SCCs Ki67 was more abundantly present in cohesive tumor areas that were devoid of CCHCR1 expression." (PMID 22218424, 2012). "In order to determine whether different bioactive agents alter CCHCR1 mRNA expression, we treated HaCaT cell cultures with tumor promoters, oxidative stress inducers, and agents involved in psoriatic inflammation." (PMID 19551138, 2009). "However, in cell culture the most atypic cells express CCHCR1 less than immortalized HaCaT cells, and tumor promotion and induced proliferation of HaCaT cells correlates with reduced CCHCR1 expression." (PMID 19551138, 2009). "Moreover, the tumor promoters okadaic acid and menadione downregulated CCHCR1 mRNA." (PMID 19551138, 2009). "All five samples studied were cyclin-D1 positive: however, its expression was not as strong as that of CCHCR1 and more concentrated to the centre of the tumor nests (data not shown)." (PMID 19551138, 2009). "However, in grade III SCCs Ki67 was more abundantly present also in cohesive tumor areas that were devoid of CCHCR1 expression (data not shown)." (PMID 19551138, 2009). "The most aggressive and invasive tumor cell lines (RT3, FaDu) expressed CCHCR1 mRNA less than non-tumorigenic HaCaT cells." (PMID 19551138, 2009). "However, there was negative correlation with CCHCR1 and EGFR expression in these same cell lines as well as in invasive FaDu tumor cells, suggesting that EGFR transcription was inhibited." (PMID 19551138, 2009). "The tumor promoters 12-phorbol-13-myristate-acetate (PMA) and staurosporine or the anti-estrogen tamoxifen, H2O2 producing oxidative stress, leptin, IL-6 or staphylococcal endotoxin B, activin or anisomycin, did not significantly influence CCHCR1 mRNA levels (data not shown)." (PMID 19551138, 2009).
cancer (3 papers, 2009 to 2014). A tumor composed of atypical neoplastic, often pleomorphic cells that invade other tissues. "In the present study, we have identified the human protein CCHCR1 as a specific interactor of the E2 protein from HPV16, the prevailing genotype in HPV-associated cancers." (PMID 24664238, 2014). "We identified an interaction between E2 and a cellular protein called CCHCR1, which proved highly specific for the HPV16 genotype, the most prevalent in HPV-associated cancers." (PMID 24664238, 2014). "The mRNA CCHCR1 levels were determined by a real-time PCR method with RNA probes isolated from cervical precancerous, cancer and control cells." (PMID 22218424, 2012). "In BCC, CCHCR1 was expressed especially in the cytoplasm of the palisading cancer cells of the well-defined carcinoma islands." (PMID 19551138, 2009). "As EGFR and its downstream target cyclin-D1 are involved in cancer development and possibly affected by the putative CCHCR1 pathways, we examined their expression in comparison to CCHCR1." (PMID 19551138, 2009). "The highly specific trait of CCHCR1 interaction toward the E2 protein from HPV16 suggests a potential involvement in particular features of HPV16 pathogenesis, possibly related to its high prevalence in HPV-associated cancers." (PMID 24664238, 2014). "The CCHCR1 positive cancer nests in the lower dermis were cyclin-D1 positive as well." (PMID 19551138, 2009). "The aim of the present study was the analysis of the CCHCR1 gene in precancerous and cancer lesions and in HPV positive and negative dysplasia cells." (PMID 22218424, 2012). "Proliferative cancer cells at the invasive front expressed CCHCR1, whereas the cohesive cancer cells in the middle were CCHCR1 negative." (PMID 19551138, 2009).
genetic diseases (1 paper, 2019). "The remaining genes, DPP6, INPP5F, CCHCR1, and CBFA2T3, are also associated with many genetic diseases." (PMID 31332212, 2019).
CCHCR1 also shares sentences with these, for which no sentence is quoted: adenocarcinoma (1 paper); alopecia (1); ankylosing spondylitis (1); autoimmune disease (1); Autoimmunity (1); Cirrhosis (1); colorectal cancer (1); coronary atherosclerosis (1); diabetes (1); dyslipidemia (1); follicular lymphoma (1); heart failure (1); hepatocellular carcinoma (1); HIV-1 infection (1); Hypercholesterolemia (1); hyperthyroidism (1); keratoacanthoma (1); major depressive disorder (1); non-melanoma skin carcinoma (1); non-small cell lung carcinoma (1); pneumonia (1); rheumatoid arthritis (1); squamous cell carcinoma of the head and neck (1).